GLRX2 (glutaredoxin 2)
Description:
Glutathione-dependent oxidoreductase that facilitates the maintenance of mitochondrial redox homeostasis upon induction of apoptosis by oxidative stress. Involved in response to hydrogen peroxide and regulation of apoptosis caused by oxidative stress. Acts as a very efficient catalyst of monothiol reactions because of its high affinity for protein glutathione-mixed disulfides. Can receive electrons not only from glutathione (GSH), but also from thioredoxin reductase supporting both monothiol and dithiol reactions. Efficiently catalyzes both glutathionylation and deglutathionylation of mitochondrial complex I, which in turn regulates the superoxide production by the complex. Overexpression decreases the susceptibility to apoptosis and prevents loss of cardiolipin and cytochrome c release.
Synonyms: GRX2; CGI-133; bA101E13.1
Tractability: Small molecule: a structure with a bound ligand is known. PROTAC: ubiquitination databases record sites on it; its protein half-life has been measured.
Gene: Protein-coding gene on chromosome 1 (193,090,866 to 193,106,114, reverse strand). Ensembl gene ENSG00000023572.
Subcellular location: Mitochondrion (Isoform 1); Nucleus (Isoform 2)
Subcellular location (Human Protein Atlas): Nucleoplasm; Vesicles
Gene Ontology:
Molecular function: protein binding; arsenate reductase (glutaredoxin) activity; electron transfer activity; glutathione disulfide oxidoreductase activity; protein disulfide isomerase activity; protein-disulfide reductase activity
Biological process: apoptotic process; cell differentiation; cell redox homeostasis; DNA protection; glutathione metabolic process; regulation of DNA-templated transcription; regulation of signal transduction; response to redox state; response to temperature stimulus
Cellular component: mitochondrion; nucleoplasm; nucleus
Genetic constraint (gnomAD): Loss-of-function variants: 5 observed, 5.56 expected, observed/expected ratio (o/e) 0.9, 90% interval 0.46 to 1.73. That is too few expected variants to judge how well the gene tolerates losing a copy. Missense variants: 116 observed, 91.04 expected, observed/expected ratio (o/e) 1.27, 90% interval 1.1 to 1.49. Synonymous variants: 57 observed, 37.46 expected, observed/expected ratio (o/e) 1.52, 90% interval 1.23 to 1.86.
Homologues: Orthologues: macaque GLRX2 (95% identical), chimpanzee GLRX2 (82% identical), dog GLRX2 (73% identical), rat Glrx2 (73% identical), guinea pig GLRX2 (71% identical), tropical clawed frog glrx2 (40% identical), zebrafish glrx2 (37% identical), Drosophila melanogaster Grx1 (29% identical), Drosophila melanogaster Grx1t (29% identical), Caenorhabditis elegans F10D7.3 (20% identical). Paralogues in human: GRXCR1 (17% identical), GRXCR2 (13% identical).
Diseases named in the same sentence as GLRX2 in open-access papers:
GLRX2 is named in the same sentence as 54 diseases in open-access papers, as found by Europe PMC text mining. Sharing a sentence is not in itself a finding about the gene and the disease. The quoted sentences say what the papers report.
breast carcinoma (3 papers, 2021 to 2025). "GAS5 is a well-studied down regulated lncRNA in breast cancer while GLRX2 is a protein that localizes to the mitochondria where it functions in mitochondrial redox homeostasis and is important for the protection against and recovery from oxidative stress." (PMID 34717732, 2021). "However, we found underexpression of EEF2 and GLRX2 proteins involved in ROS; MTX2 in MMO; USP30 in MIT; TSPO in MIT and PPM processes; BAX in FUS; and MTFR1L and MIEF1 in FIS compared to luminal A and basal-like breast cancer tumors." (PMID 35327574, 2022).
glioma (3 papers, 2024 to 2025). A benign or malignant brain and spinal cord tumor that arises from glial cells (astrocytes, oligodendrocytes, ependymal cells). "GLRX2 influences tumor-associated immune processes, particularly via M0 macrophages and immune checkpoint pathways in gliomas, indicating a role in shaping the TME." (PMID 41373732, 2025).
cardiac hypertrophy (2 papers, 2020 to 2024). "Glrx2 KO mice worsened high-fat diet-induced insulin resistance and weight gain and developed cardiac hypertrophy and hypertension with impaired mitochondrial ATP production." (PMID 32948023, 2020). "Deletion of Glrx2 in mice hearts results in cardiac hypertrophy and fibrosis as well as hypertension, while Glrx3 KO in mice results in cardiac hypertrophy and heart failure." (PMID 32948023, 2020). "In addition to Glrx, Glrx2 and Glrx3 have also been shown to play a role in cardiac hypertrophy." (PMID 32948023, 2020).
colon adenocarcinoma (2 papers, 2024 to 2025). "High GLRX2 expression correlates with better prognosis and survival in early-stage colon adenocarcinoma (87% in stage I vs. 1% in stage III), acting as an independent prognostic marker." (PMID 41373732, 2025).
colorectal cancer (2 papers, 2024 to 2025). A primary or metastatic malignant neoplasm that affects the colon or rectum. "Recent work has demonstrated that over-expression of glutaredoxin-2 (Glrx2), the thiol oxidoreductase that mediates reversible S-glutathionylation reactions in mitochondria, is a prognostic factor for the survival of patients with colorectal cancer." (PMID 40358176, 2025).
fatty liver disease (2 papers, 2024). A reversible condition wherein large vacuoles of triglyceride fat accumulate in liver cells via the process of steatosis. "Metabolism of iron and participation in protein glutathionylation/deglutathionylation, GLRX2 deficiency has been elucidated to increase oxidative stress cellular sensitivity in metabolic dysfunction-associated fatty liver disease." (PMID 39314522, 2024).
left ventricular hypertrophy (2 papers, 2014 to 2020). Enlargement of the LEFT VENTRICLE of the heart. "While not many studies have researched Glrxs in the human heart, one study has shown that low levels of Glrx2 appear to be correlated with myocardial infarction, left ventricular hypertrophy, as well as fibrosis." (PMID 32948023, 2020).
bladder cancer (1 paper, 2025). "GLRX2 is upregulated in bladder cancer and contributes to diagnostic models, suggesting a pro-tumorigenic role." (PMID 41373732, 2025).
colon cancer (1 paper, 2025). "Serum GLRX2 levels in colon cancer patients correlate with survival." (PMID 41373732, 2025).
dilated cardiomyopathy (1 paper, 2013). Cardiomyopathy which is characterized by dilation and contractile dysfunction of the left and right ventricles. "Malfunction of mitochondrial thioredoxin reductase causes dilated cardiomyopathy in man and aggravates ischemia-reperfusion injury in mice, while overexpression of glutaredoxin-2 reduces ischemia-reperfusion injury in mice." (PMID 24053891, 2013).
heart failure (1 paper, 2013). Inability of the heart to pump blood at an adequate rate to meet tissue metabolic requirements. "We think that the up-regulation of Glrx2 is most likely due to the auto-adjustment of the heart system to compensate for heart failure." (PMID 24564975, 2013). "However, the endogenous mechanisms in those heart failure rats were not able to raise Glrx2 up to a level high enough to prevent the onset from happening." (PMID 24564975, 2013).
non-alcoholic fatty liver disease (1 paper, 2025). "Using a mouse model ablated for the Glrx2 gene (Glrx2−/−), we were able to show that the induction of KGDH S-glutathionylation protects male C57Bl6N mice from the manifestation of non-alcoholic fatty liver disease (NAFLD) caused by dietary fat overload." (PMID 40358176, 2025).
Obesity (1 paper, 2020). Accumulation of substantial excess body fat. "Our group recently documented that male mice containing a deletion for one copy of the glutaredoxin-2 (Grx2) gene were completely protected from developing diet-induced obesity (DIO)." (PMID 32993466, 2020).
periodontitis (1 paper, 2024). An acute or chronic inflammatory process that affects the tissues that surround and support the teeth. "The results of the present study revealed a causal association between periodontitis and medium-chain specific acyl-CoA dehydrogenase (MCAD), malonyl-CoA decarboxylase (MLYCD), glutaredoxin 2 (Grx2), oligoribonuclease (ORN), and pyruvate carboxylase (PC)." (PMID 39063197, 2024).
Sepsis (1 paper, 2018). Sepsis is defined as life-threatening organ dysfunction caused by a dysregulated host response to infection. "At enrollment, sepsis was associated with significant increases in the expression of mRNAs related to redox metabolism (myeloperoxidase, 64-fold; PRDX3, 2.6-fold; SOD2, 2.2-fold) and redox-responsive genes (FOXM1, 21-fold; SELS, 16-fold; GLRX2, 3.4-fold)." (PMID 29540208, 2018).
Sjögren’s syndrome (1 paper, 2025). "In the field of stem cell therapy for Sjögren’s syndrome, hypoxic ADSC-derived exosomes attenuate skin damage caused by primary Sjögren’s syndrome through GLRX2 delivery and ferroptosis suppression." (PMID 40934008, 2025).
cancer (9 papers, 2016 to 2025). A tumor composed of atypical neoplastic, often pleomorphic cells that invade other tissues. "Based on the results of pan-cancer analysis, we found that GLRX2, NMT1, PPP2R2B and TRAF3IP3 exhibited a dysregulated level in many types of tumors, highlighting their potential roles in tumor progression." (PMID 38409085, 2024). "Glutaredoxin 2 (Grx2; Glrx2) is an enzyme that is of special interest in cancer research." (PMID 38256132, 2024). "Similarly, mitochondrial glutaredoxin-2 (Grx2) has been shown to have an anti-apoptotic outcome in cancer cells." (PMID 32185131, 2020).
tumor (5 papers, 2020 to 2025). "SOD1, GLRX2, PRDX6, and GLRX3 genes were also overexpressed in MM patients compared to normal plasma cells, confirming that the redox status is unbalanced in tumour vs. normal cells." (PMID 33114738, 2020).
GLRX2 also shares sentences with these, for which no sentence is quoted: asthma (2 papers); cardiac disease (2); cataract (2); hepatocellular carcinoma (2); Hypertension (2); lupus (2); neuroblastoma (2); abortion (1); adenocarcinoma (1); asphyxia (1); autoimmune bullous skin disease (1); Autoimmunity (1); cervical cancer (1); clear cell renal carcinoma (1); colorectal adenocarcinoma (1); dementia (1); developmental delay (1); eosinophilia (1); hypoxia (1); infection (1); Insulin resistance (1); ischemia (1); lung carcinoma (1); lymphoma (1); mesothelioma (1); metabolic syndrome (1); myocardial infarction (1); neurological disorders (1); ovarian carcinoma (1); pancreatic cancer (1).
A further 6 diseases each share a sentence with GLRX2 in 1 paper.